MSTN (myostatin)
Diseases named in the same sentence as MSTN in open-access papers (continued):
Sharing a sentence is not in itself a finding about the gene and the disease.
Obesity (continued). "In MSTN knockout mice (MSTN-/-), the absence of MSTN results in increased skeletal muscle mass, reduced fat tissue, increased insulin sensitivity, enhanced fatty acid oxidation, and an elevated resistance to obesity, whereas overexpression of myostatin induces muscle atrophy." (PMID 29228005, 2017). "Analyzing sorted LECs from HFD-fed C57BL/6J obesity-prone mice showed that the expression of VEGFR3 is decreased in obesity, while HFD-fed BALB/cJ and myostatin null (MSTNln) obesity-resistant mice had no significant changes to their lymphatics." (PMID 38201272, 2023). "Nevertheless, although myostatin was not correlated with bone turnover markers, we cannot exclude the possibility that it contributed to the reduced bone formation, particularly in the women with class III obesity who presented concomitantly higher myostatin and lower osteocalcin levels." (PMID 32316563, 2020).
Cachexia (102 papers, 2007 to 2026). Severe weight loss, wasting of muscle, loss of appetite, and general debility related to a chronic disease. "On the other hand, analyses on mice models have shown that myostatin overexpression led to cachexia, a wasting syndrome associated with muscle wasting." (PMID 39585121, 2024). "While animal models have confirmed that high levels of myostatin are associated with muscle atrophy, in studies of humans with cachexia, the results have been more mixed." (PMID 36269458, 2022). "The addition of a soluble antagonist of ACVRIIB that antagonizes MSTN signaling also reduced cancer-associated cachexia and reversed muscle wasting." (PMID 35812316, 2022). "In the multivariable logistic regression, RA with high myostatin levels (≥17 ng/mL) was found to increase the risk of cachexia (OR = 2.79, 95% CI: 1.24-6.29; p = 0.01) and LSMM (OR = 3.04, 95% CI: 1.17-7.89; p = 0.02)." (PMID 35592686, 2022). "In various disease models, including cancer-associated cachexia, pharmacological blockade of the MSTN/activin- ActR2B pathway has been shown to prevent loss of muscle mass and strength." (PMID 34500839, 2021). "Our previous study has demonstrated that by attenuating NF‐κB binding to Mstn promoter, SIRT6 downregulates myostatin expression and muscle loss in in vitro models of cachexia." (PMID 34212132, 2021). "Muscle Myostatin expression was initially shown to decline after weight loss; however, in chronic diseases accompanied by cachexia such as chronic obstructive pulmonary disease (COPD) patients with higher Myostatin levels had a lower BMI." (PMID 32784522, 2020). "Myostatin upregulation was observed in the pathogenesis of muscle wasting during cancer-associated cachexia." (PMID 27916875, 2016). "MAPKs activation has been previously associated with muscle wasting, and altered AKT-dependent anabolism and enhanced myostatin expression have both been implicated in cachexia." (PMID 27259276, 2016). "For example, inhibin-deficient mice develop adrenal tumors and cachexia, and myostatin administration induces cachexia." (PMID 26172047, 2015). "During pathological loading of the heart, increased cardiac production of myostatin may be maladaptive, considering that it has systemic effects associated with cachexia." (PMID 38136649, 2023). "Although the mechanisms of muscle loss are not clearly defined in either condition, the results obtained from experimental rodent models and clinical trials indicate that MSTN inhibition offers a promising means of controlling muscle loss and cancer-related cachexia." (PMID 35812316, 2022). "Importantly, NRG-1β altered the directionality of at least 85 genes associated with cachexia, including myostatin, which negatively regulates myoblast differentiation by down-regulating MyoD expression." (PMID 35625411, 2022). "Similarly, myostatin overexpression was implicated in cachexia development in both mice and humans, and myostatin blockade was able to preserve muscle mass and increase survival in cachexia mouse models." (PMID 35727341, 2022). "Likewise, myostatin (Mstn), a negative regulator of muscle growth and development that is associated with cachexia, is increased in G609G mice, and HFD does not reduce its levels." (PMID 30548460, 2019). "Dr Lee went on to extensively study myostatin, and in subsequent papers demonstrated the loss of white fat that occurs upon induction of hypermuscularity by myostatin inhibition, and that administration of myostatin was sufficient to cause a phenotype reminiscent of cachexia." (PMID 22676848, 2012). "Additionally, Anamorelin may also alleviate muscle wasting caused by cachexia by inhibiting the signaling of cytokines such as Myostatin, Activin-A, and TGF-β, which are considered important negative regulators of skeletal muscle mass." (PMID 39101140, 2024).
Cachexia (continued). "However, in order to be able to diagnose myostatin induced cachexia, to identify patients at risk for muscle wasting or bad prognosis and to guide therapy, it would be necessary to determine the serum myostatin concentration in a reliable, very specific and high-throughput manner." (PMID 24260393, 2013). "As DCN binds to and directly inhibits myostatin, a potent inhibitor of muscle growth, it has been suggested as a potential target for maintaining the muscle mass in cachexia." (PMID 41392017, 2026). "The protein levels of MuRF1, MAFbx32, and MSTN that were increased in the cancer cachexia group were restored in the LJFE‐treated group." (PMID 40672545, 2025). "Myostatin is often overexpressed in the muscles and plasma of patients with cachexia and in animal models." (PMID 40869331, 2025). "Exercise confers robust molecular benefits in CRC-induced cachexia, likely mediated through modulation of the myostatin–FOXO–MuRF-1/Atrogin-1 signaling axis." (PMID 41303857, 2025). "Conversely, follistatin, a muscle-derived exerkine that binds and neutralizes myostatin and activin A, is significantly reduced in cachexia." (PMID 40869331, 2025). "Taken together, these results suggest that, according to previous findings, IL6 is the main driver of muscle atrophy in the experimental model of C26‐induced cachexia, whereas TNFα and myostatin only have marginal roles." (PMID 40448398, 2025). "Myostatin and its activin receptors (together with lipocalin A and growth differentiation factor GDF15) have been described as mediators of cachexia–anorexia syndrome associated with malignancies together with circulating inflammatory factors." (PMID 39683624, 2024). "In contrast, extracellular activators of the catabolic signaling exerted by pSmad2/3, as myostatin and activin A have been found to be highly expressed in cachectic patients and to induce muscle wasting in various murine models of cachexia." (PMID 38052214, 2023). "Discovery of a role of myostatin in reduction in skeletal muscle mass called attention to its role in the development of cachexia." (PMID 38136649, 2023). "Increased levels of STAT3 phosphorylation, C/EBPδ, and myostatin were observed in the Lewis lung carcinoma (LLC) tumor-induced cachexia mouse model." (PMID 37217930, 2023). "On the other hand, both human and animal data indicate that myostatin is involved in the development of the cardiac cachexia and heart fibrosis in the course of chronic heart failure." (PMID 38136649, 2023). "Activin type-2 receptor (ActRIIB) antagonism and/or MSTN antibodies have emerged as viable therapeutic targets for the treatment of cachexia, although the broad clinical applications of these potential treatment strategies have not been demonstrated." (PMID 35565236, 2022). "In a cohort of patients with colorectal or lung cancer, concentrations of myostatin were found to be significantly lower in patients with cancer cachexia compared with weight-stable counterparts." (PMID 36269458, 2022). "As a result of these findings, MSTN has emerged as an important developmental target for the treatment of cachexia and muscle wasting disorders." (PMID 35565236, 2022). "For example, SIRT6 inhibits myostatin expression by mitigating NF-κB binding to the myostatin promoter, which is beneficial for maintaining muscle function and preventing chronic heart failure-induced cachexia." (PMID 36465178, 2022). "In a study conducted on animals with tumor-induced cachexia, the expression of MSTN was up-regulated, and another study showed that blockage/inhibition of MSTN in animals with cancer cachexia prevented muscular atrophy without affecting tumor growth." (PMID 35812316, 2022). "Activin-A and Myostatin are members of the transforming growth factor beta (TGF-β) family that have been identified as potential tumour-derived catabolic factors in cachexia." (PMID 36269458, 2022).
Cachexia (continued). "Puzzlingly, it has been reported that circulating levels of myostatin are reduced, in colorectal and lung cancer patients with cachexia." (PMID 36078078, 2022). "MSTN is released primarily by SM and negatively regulates muscle mass, as demonstrated by the development of cachexia in rodents’ systemically administered MSTN." (PMID 35565236, 2022). "Strategies based on the regulation of IGF-1 and the suppression of MSTN increase muscle growth and aid recovery from cachexia, and thus, drugs and inhibitors used to treat cachexia should have anti-inflammatory and appetite-stimulating properties." (PMID 35565236, 2022). "In the case of myostatin, all the drugs retrieved are in clinical trials for phenotypes related to cachexia." (PMID 34832866, 2021). "The role of myostatin in muscular atrophy and muscle wasting was also determined in mice that developed cachexia in response to myostatin overexpression." (PMID 33802348, 2021). "In the past decades, strategies for cachexia therapy mainly focused on the development of new drugs, including ghrelin and ghrelin receptor agonists, myostatin antagonists, inflammatory cytokine neutralizing antibodies, and natural product extracts." (PMID 34229732, 2021). "Physical activity and nutritional status are also confounding factors for the adoption of myostatin as a biomarker of cachexia." (PMID 33445790, 2021). "Myostatin has been found to be upregulated in cancer, heart disease, HIV, and aging, and systemic administration of myostatin caused cachexia in rodents." (PMID 32858949, 2020). "Accordingly, downregulation of p-Akt and p-FoxO3 accompanied by myostatin and activin A overproduction in the muscle were seen in mice with bladder cancer, implying myostatin involvement in cachexia triggered by various cancer types." (PMID 33329046, 2020). "Myostatin can induce the expression of MuRF1 and Atrogin1/MAFbx as well as Twist1, and genetic inactivation of myostatin has shown to protect against cancer-induced cachexia." (PMID 32655411, 2020). "In clinical therapy for muscle wasting in cachexia patients, myostatin inhibitors have been widely investigated for therapeutic treatments; thus, the myostatin inhibitor SRP4623P was also used as a positive control to prevent muscle wasting." (PMID 30718259, 2019). "Findings from several groups indicate that myostatin expression is usually increased during conditions such as cachexia)." (PMID 29709011, 2018). "Previous studies have reported that myostatin and activin signaling in muscle increases in patients with cancer suffering from cachexia and in experimental cancer cachexia." (PMID 29731967, 2018). "In some cases, the symptoms of cachexia have been alleviated by inhibiting tumor growth, stimulating appetite, and removing tumor-derived pro-cachectic factors such as IL-6 and myostatin." (PMID 29662645, 2018). "In contrast, high levels of myostatin or activin A have been reported to promote cachexia and the related muscle wasting in mice." (PMID 27462398, 2016). "Intriguingly, both myostatin and GDF15 have been associated with cachexia, a common and often fatal condition which occurs most commonly in advanced cancer." (PMID 27916875, 2016). "Overproduction of myostatin and activin A has been observed in both cancer patients suffering from cachexia and the animal models of cancer cachexia." (PMID 26600425, 2015). "On the other hand, myostatin inhibition, IL-6 antagonism and synthetic ghrelin administration are examples of promising treatments in cachexia animal models." (PMID 24782779, 2014). "The transforming growth factor-β-related protein myostatin, a key regulator of muscle growth, has been considered an important mediator of cardiac-induced skeletal muscle wasting and cachexia in animal studies." (PMID 25330387, 2014). "On the other hand, nude mice expressing high-level of recombinant myostatin had a cachexia-like phenotype with reduction in both muscle and fat." (PMID 25254550, 2014).
Cachexia (continued). "In order to further test our assay and measure myostatin in patients with cachexia or muscle wasting, we assessed serum prodomain levels in two additional patient cohorts." (PMID 24260393, 2013). "A causal link between skeletal muscle wasting and activation of MSTN signalling has, perhaps, been more convincingly established in the cachexia seen in the setting of heart failure." (PMID 21798080, 2011). "The finding that overexpression of MSTN in mice could lead to the development of a cachexia-like syndrome characterized by an extensive loss of fat and muscle raised two important questions about potential therapeutic applications of targeting this pathway in patients with cachexia." (PMID 21798080, 2011). "One possible explanation for these findings is that myostatin, produced by skeletal muscle, may have decreased circulating levels due to reductions in muscle mass during cancer cachexia." (PMID 39764565, 2025). "Many cancer patients experiencing cachexia have elevated blood levels of myostatin and activin." (PMID 38334644, 2024). "Similarly, injection with myostatin-producing cells reduces skeletal muscle mass in mice, leading to wasting syndrome in the long run." (PMID 38136649, 2023). "Myostatin is another important pathway that leads to muscle atrophy in certain cachexia models." (PMID 37217930, 2023). "Muscle myostatin (MSTN) expression is upregulated in some preclinical cancer cachexia models, which could contribute to increased muscle protein breakdown." (PMID 36428623, 2022). "Furthermore, a study on a myostatin antagonist used to counteract cardiac cachexia secondary to CHF has also been published." (PMID 35049831, 2022). "Evaluate the value of serum myostatin as a biomarker of cachexia and low skeletal muscle mass (LSMM) in RA patients, along with whether high serum myostatin is associated to these conditions after adjusting for potential confounders." (PMID 35592686, 2022). "Thus, stimulating IGF-1 and blockading MSTN using natural compounds would promote muscle hypertrophy and provide a possible means of managing cachexia." (PMID 35565236, 2022). "MSTN expression is increased in the muscle of tumor-induced cachexia." (PMID 35565236, 2022). "In addition, myostatin, which can inhibit myogenesis, was induced in the cachexia group and suppressed upon BGM exposure." (PMID 33802674, 2021). "Further research should also examine whether the myostatin/activin blockage repletes NAD+ and Nrk2 deficiencies via direct action or by interfering with cachexia-altered signalling events." (PMID 32599075, 2020). "Additionally, intervention at the activin type II receptors level via the use of the neutralizing Ab CDD866 is effective at protecting from cancer-induced cachexia through the blockade of circulating ligands (anti myostatin Ab or soluble ActRIIB-Fc)." (PMID 27462398, 2016). "Furthermore, this treatment brought elevated serum levels of myostatin back to normal and attenuated cachexia, independently of pro-inflammatory cytokine levels." (PMID 26856534, 2016). "Radiation-induced cachexia may share similar pathways of protein catabolism and activation of the myostatin/activin signaling as in other cachetic diseases." (PMID 27029502, 2016). "Myostatin is upregulated in cachexia and in states of muscle paralysis." (PMID 24404136, 2014). "Since beta-blocker and ACE inhibitors were previously shown to mediate a positive influence on cachexia in heart failure, this treatment might also reduce myostatin expression." (PMID 24260393, 2013). "The identification of several components of the myostatin-signalling pathway had important implications with respect for testing the therapeutic value of a myostatin antagonist in muscle wasting disorders such as Duchenne muscular dystrophy cachexia and age-related sarcopenia." (PMID 23046573, 2012).